PHF5A (PHD finger protein 5A)
Diseases named in the same sentence as PHF5A in open-access papers (continued):
Sharing a sentence is not in itself a finding about the gene and the disease.
tumor (continued). "Microarray and bioinformatics analyses revealed that PHF5A depletion led to dysregulation of multiple tumor signaling pathways; selected factors in key signaling pathways were verified in vitro." (PMID 29566713, 2018). "Collectively, these results were in line with the prominent role of IGFBP3 as a tumor suppressor, and also revealed broad regulatory effects of PHF5A on cellular functions through multiple signaling pathways." (PMID 29566713, 2018). "Expectedly, PHF5A knockdown in LAC cells not only decreased tumor growth, but also significantly arrested cell cycle progression, conforming with the defined roles of PHF5A in yeasts described in previous reports." (PMID 29566713, 2018). "Although PHF5A was also down regulated in the human tumor samples, but unexpectedly, it was more down regulated in the human benign samples." (PMID 23675859, 2013). "For PHF5A all tumor classes were up regulated compared to the benign samples, where type II tumors differed most from the benign samples." (PMID 23675859, 2013). "PHF5A is a tumor promoter in ESCC, which is dependent on VEGFA and PI3K/AKT signaling." (PMID 38429756, 2024). "PHF5A is found to be a key splicing factor as the subunit of splicing factor 3b (SF3b) component, which is involved in the formation of U2 small nuclear ribonucleoprotein (U2 snRNP) splicing complex to promote tumor progression." (PMID 38429756, 2024). "Whether roles of PHF5A played in the angiogenesis may help us to further understand the principal contribution of the tumor growth." (PMID 38429756, 2024). "The findings that PHF5A may participate in tumor immune evasion were concurrently supported by the finding that immunotherapy worked better for HCC patients with low PHF5A expression in the validation study." (PMID 39030507, 2024). "PHF5A was revealed to participate in a couple of critical cell events in cancer, indicating that PHF5A may modulate tumor progression via diverse mechanisms." (PMID 39030507, 2024). "PHF5A could serve as a tumor biomarker related to prognosis across cancers, especially HCC, and shed new light on the development of novel therapeutic targets." (PMID 39030507, 2024). "PHF5A expression exhibited a close link to tumor size and BCLC stage (both P < 0.05)." (PMID 39030507, 2024). "Subsequent studies have shown that PHF5A is a key splicing factor involved in tumor progression." (PMID 36609277, 2023). "The link of tumor clinical stages with PHF5A expression were also analyzed thoroughly." (PMID 37845358, 2023). "Additionally, we noticed that PHF5A expression showed a correlation with the grade of 6 different tumor types." (PMID 37845358, 2023). "In addition, the relevance between PHF5A expression and tumor metastasis was preliminarily investigated." (PMID 37845358, 2023). "As the PHF5A expression increased, the tumor grade also developed in an upward direction." (PMID 37845358, 2023). "According to our findings, PHF5A played a critical role in tumor immunity and it might be an excellent target for anticancer immunotherapy." (PMID 37845358, 2023). "Hence, PHF5A is an important subunit of U2 snRNPs playing pivotal role in regulation of pre-mRNA splicing/alternative gene splicing with resultant improved tumor progression, propagation and metastasis based on specific branch point sequence recognition." (PMID 37483794, 2023). "The examination indicated that PHF5A may impact tumor development through the involvement of spliceosome, ribosome, proteasome, DNA replication, mismatch repair, cell cycle, RNA degradation, and transport pathways." (PMID 37845358, 2023). "In LIHC, as the expression of PHF5A increased, the tumor grade also elevated." (PMID 37845358, 2023). "Accordingly, it can be inferred that PHF5A has the capacity to act as an immunotherapy target or biomarker for different types of cancer, and can also function as an indicator for the effectiveness of tumor immunotherapy." (PMID 37845358, 2023).
tumor (continued). "Moreover, we also confirmed a decreased tumor growth in vivo and a suppressed cell invasion and migration capacity in vitro by PHF5A depletion." (PMID 29566713, 2018). "Tumor growth, size, and weight were significantly reduced in the PHF5A knockdown group." (PMID 29566713, 2018). "PHF5A silencing was also found to inhibit LAC tumor growth in nude mice." (PMID 29566713, 2018). "Since our clinical results and TCGA data consistently indicated that PHF5A expression was not only positively correlated with T stage, but also with lymph node metastasis, we hypothesized that PHF5A could play a role in tumor invasion and migration." (PMID 29566713, 2018). "Thus, we speculated that PHF5A might promote tumor growth by facilitating RNA transcription and degradation, promoting DNA replication and repair and driving the cellular processes." (PMID 37845358, 2023). "Furthermore, we established a subcutaneous xenograft mouse model of HNSCC using FaDu cells infected with empty vector (EV) and PHF5A overexpression (OE) plasmids, which showed that the tumours in the PHF5A overexpression group grew faster and weighed more than those in the empty vector group." (PMID 37434235, 2023). "Furthermore, we investigated the connection between PHF5A expression and tumor grade." (PMID 37845358, 2023). "Consequently, it can be inferred that PHF5A has the capacity to act as an immunotherapy target or biomarker for different types of cancer, and can also function as an indicator for the effectiveness of tumor immunotherapy." (PMID 37845358, 2023). "PHF5A targeting might be helpful in identification of diverse splicing pathways and some interconnected extremely sheltered splicing factors responsible for tumor progression through undefined molecular mechanisms." (PMID 37483794, 2023). "Thus, the management of tumor malignancies developed from reoccurrence of the tumor, tumor metastasis, and potential treatment resistance through consideration of PHF5A as a potential therapeutic target for the resolution of clinical crises becomes extremely imperative." (PMID 37483794, 2023). "This suggests that PHF5A is closely involved in the ERK signalling pathway, which plays a role in the development of tumours." (PMID 39212334, 2025). "To analyze the synergistic roles of PHF5A and VEGFA proteins in ESCC cell progression, we firstly overexpressed PHF5A to reconfirm the tumor promotion of PHF5A in ESCC." (PMID 38429756, 2024). "Hence, we speculated that PHF5A might have a link with tumor immune evasion." (PMID 39030507, 2024). "The biological phenotype studies revealed that PHF5A promoted ESCC cells proliferation and metastasis in vitro, as well as the deriving of tumor growth in vivo." (PMID 38429756, 2024). "The expression of PHF5A was detected in HNSCC cells, TCGA data and a separate primary tumour cohort." (PMID 37434235, 2023). "The mRNA and protein levels of PHF5A were significantly upregulated in both TCGA mRNA–seq data set and our own NSCLC patient tumor samples, and the expression level of PHF5A was significantly negatively correlated with patient outcomes in LUAD but not in LUSC." (PMID 30932358, 2019). "We found that the mRNA expression level of PHF5A was significantly increased in both LUAD and LUSC tumor tissues compared with normal tissues." (PMID 30932358, 2019). "IHC revealed that PHF5A was significantly upregulated in LAC tissues and closely related to tumor progression and poor prognosis in LAC patients." (PMID 29566713, 2018). "The expression of PHF5A in LAC tissues and adjacent non-tumor (ANT) tissues was investigated using immunohistochemistry of a tissue microarray, qRT-PCR, western blot and bioinformatics." (PMID 29566713, 2018). "For Phf5a significant differences were found in comparisons between EACs developed in the BN and those in the SPRD background with a lower expression in the tumor cell lines derived from the progenies of the (BDIIxBN)xBDII crosses (P<0.05)." (PMID 23675859, 2013).
tumor (continued). "Consistently, the data of qRT-PCR showed that the mRNA level of PHF5A in GC tumor tissue was significantly higher than that in normal tissue (P = 0.017)." (PMID 36609277, 2023). "PHF5A and PRPF38A play an important role in regulating tumour proliferation and migration." (PMID 36434140, 2022). "The aim of this study was to investigate the expression of Phf5a and its effect on Gja1 expression in tumor and non-malignant cell lines derived from the BDII rat model with different genetic backgrounds." (PMID 23675859, 2013). "Moreover, PHF5A expression was related to the examined immunoregulation-related genes of chemokine receptor, chemokine and MHC, which further demonstrated its potential immune function in different kinds of tumor." (PMID 37845358, 2023). "In LUAD, the expression level of PHF5A was stained highly in approximately 63.33% (38/60) of the tumor tissues but in only 3.33% (2/60) of the nontumor tissues; in LUSC, the percentage of high expression of PHF5A was 60.6% (40/66) and 4.55% (3/66) in tumor and normal tissues, respectively." (PMID 30932358, 2019). "First, we analyzed the expression of PHF5A in LUSC patients using both TCGA data sets and our own tumor tissue samples and found that PHF5A was upregulated in LUSC patients but was not significantly correlated with patient outcomes, and this finding differed from those observed in LUAD." (PMID 30932358, 2019). "In the rat tumor set, comparison of the gene expression of Phf5a and Gja1 between the EAC and NME samples showed a slight, but not significant, decrease in in expression of Phf5a in the EAC cell lines." (PMID 23675859, 2013).
cancer (18 papers, 2014 to 2025). A tumor composed of atypical neoplastic, often pleomorphic cells that invade other tissues. "In this cancer type, the loss of PHF5A led to the retention of intron 5 in FASTK, resulting in a non‐functional protein (FASTK‐short)." (PMID 39212334, 2025). "It seems that PHF5A was associated with different apoptotic pathway and alternative splicing in several cancer types." (PMID 38429756, 2024). "Here, the present results revealed that PHF5A expression was linked to main pathological stages of 3 types of tumors, and was associated with 2 cancers in the M stage and 6 cancers in the N stage." (PMID 37845358, 2023). "The abnormal expression of PHF5A in tumors has been observed to be linked to the genesis and progression of cancer in numerous studies." (PMID 37845358, 2023). "The figure reflected that PHF5A expression was notable linked to infiltrating immune cell levels for majority types of cancer." (PMID 37845358, 2023). "We selected several cancers in which the prognosis was notable linked to PHF5A promoter methylation levels." (PMID 37845358, 2023). "Combining bioinformatics results and subsequent experimental data, the inter-relationships and pathways of PHF5A with cancer associated genes were constructed." (PMID 29566713, 2018). "In short, PHF5A is a potential diagnostic, prognostic, and immunological biomarker in pan-cancer." (PMID 37845358, 2023). "PHF5A has been proven to be associated with transcription and splicing activities in previous studies, and an increasing amount of evidence indicates that it has a significant influence on the initiation and advancement of various types of cancers." (PMID 37845358, 2023). "This enhanced expression pattern of PHF5A and similar survival prognosis has also been described for other cancer entities, highlighting PHF5A as a critical gene for cancer progression." (PMID 39212334, 2025). "Together with abnormal cell proliferation, typical for cancer cells, these are two very important properties we were able to inhibit by a knockdown of PHF5A." (PMID 39212334, 2025). "This study depicted the role of PHF5A across cancers from several public databases, which was followed by validation in HCC from the viewpoints of mRNA/protein expression, prognosis, immune infiltration, pathway enrichment, angiogenesis and treatment response." (PMID 39030507, 2024). "For instance, PHF1 engages with PRMT5–WDR77 and CRL4B complexes to promote cancer progression, while PHF5A’s interaction with the SF3b spliceosome and PAF1 impacts apoptotic pathways and cellular behavior across various cancers." (PMID 38813086, 2024). "The expression model of PHF5A was also true in CCA when we expanded experimental validation to other cancer types." (PMID 39030507, 2024). "This study provides a comprehensive understanding of the biological function of PHF5A in the carcinogenesis and progression of various cancers." (PMID 39030507, 2024). "This study revealed that PHF5A was highly linked to the TME and immune cell infiltration in many cancers." (PMID 39030507, 2024). "Here, the action of PHF5A in various cancers was systematically evaluated using multiple public databases." (PMID 37845358, 2023). "Results indicated up-regulated expression of connexin α1gene and PHF5A in human endometrial cells with its down-regulated expression in rat endometrial cells in comparison to benign cancer tissues." (PMID 37483794, 2023). "In this finding, mRNA expression analysis indicated that PHF5A exhibited a notably elevated levels in 21 types of cancer." (PMID 37845358, 2023). "Firstly, we analyzed tumors with M-stage data in TCGA and discovered a notable correlation of M-stage with PHF5A expression in 2 cancer types, namely ACC and TGCT." (PMID 37845358, 2023).
cancer (continued). "The current review briefly overviews the structural and functional attributes of PHF5A along with its hitherto described role in the propagation of cancer malignancies and its future concern as a potential therapeutic target for cancer management/treatment." (PMID 37483794, 2023). "In present study, we applied various bioinformatics methods to systematically analyze PHF5A in pan-cancer." (PMID 37845358, 2023). "To summarize, the present investigation confirmed that the PHF5A expression was elevated in the majority of tumors, emphasizing a significance of PHF5A expression for the clinical assessment and prognosis of different types of cancers." (PMID 37845358, 2023). "Pladinolide B and Sliceostatin A are reported to exhibit anti-cancer attributes by precisely modulating the PHF5A and SF3B capability of identifying the branch point sequences constituting pre-mRNA." (PMID 37483794, 2023). "Subsequently, correlation of molecular and immune subtypes in cancers with PHF5A expression was demonstrated." (PMID 37845358, 2023). "PHF5A knockdown indicated the prohibition of cancer cells via the AKT/mTOR signaling pathway with eventually enhanced apoptosis and reduced proliferation/migration of cancer cells." (PMID 37483794, 2023). "Through our analysis, we gained a thorough comprehension of the roles that PHF5A played in the development and prognostication of various kinds of cancer." (PMID 37845358, 2023). "Plant homeodomain (PHD)-finger domain protein PHF5A has been demonstrated to play a promoting role in a variety of cancers." (PMID 36609277, 2023). "We further conducted separate evaluations of PHF5A-related signaling pathways in 32 cancers from TCGA using GSEA." (PMID 37845358, 2023). "On the other hand, the opposite trend was observed in the remaining 5 types of cancer, including those in which PHF5A acted as a protective factor, such as KIRC and LUSC." (PMID 37845358, 2023). "In-vitro PHF5A silencing depicted overexpression of FASTK protein that assisted FAS-mediated apoptosis with ultimate suppression of cancer cell proliferation, invasion, and progression in-vivo." (PMID 37483794, 2023). "All these data allowed the authors to conclude that in cancer cells, the complex PHF5A–SF3b binds the H3K4me3-containing promoters and then is recruited by the transcriptional machinery facilitating the AS of FASTK to yield the inactive variant." (PMID 35158828, 2022). "PHF5A is also involved in an acetylation-related AS disturbance in cancer cells by a different and complex mechanism." (PMID 35158828, 2022). "PHD finger-like domain-containing protein 5A (PHF5A) is acetylated at lysine 29 by p300 to promote cancer cell capacity for stress resistance and consequently, contributes to colon carcinogenesis." (PMID 35004688, 2021). "Disease and function enrichment analyses indicated marked alterations for each category between control and PHF5A knockdown H1299 cells, and found that “Cancer” ranked first, while “Cell cycle” was included in the significant categories." (PMID 29566713, 2018). "Similarly, PHF5A, by modulating splicing and chromatin structure, affects gene expression that undermines apoptosis, promoting cancer progression." (PMID 38813086, 2024). "PHF5A has a critical function in diverse cancers and might be identified as an emerging prognostic marker and therapeutic target." (PMID 39030507, 2024). "Total of 50 proteins that bind to PHF5A though experimental verification and the top 100 PHF5A expression-correlated genes were acquired to comprehend the involvement of PHF5A in initiation and progression of cancers." (PMID 37845358, 2023). "Thus, PHF5A consideration as a potential therapeutic target in cancer treatment based on its pivotal oncogenic regulation of cancer cells proliferation, invasion, migration." (PMID 37483794, 2023).